IL18RAP (interleukin 18 receptor accessory protein)
Diseases named in the same sentence as IL18RAP in open-access papers (continued):
Sharing a sentence is not in itself a finding about the gene and the disease.
cervical squamous cell carcinoma (1 paper, 2023). A squamous cell carcinoma arising from the cervical epithelium. "Uveal melanoma (UVM), UCEC, THYM, SKCM, sarcoma (SARC), LIHC, LGG, cervical squamous cell carcinoma and endocervical adenocarcinoma (CESC), BRCA, and ACC all demonstrated significant hazard ratios (HRs) for IL18RAP, with UVM having the highest HR (12.258)." (PMID 37698530, 2023).
cholangiocarcinoma (1 paper, 2023). A carcinoma that arises from the intrahepatic biliary tree (intrahepatic cholangiocarcinoma) or from the junction, or adjacent to the junction, of the right and left hepatic ducts (hilar cholangiocarcinoma). "The results demonstrated that the IL18RAP expression levels and DNA methylation were negatively correlated in 15 cancers, including UVM, THCA, TGCT, BRCA, PRAD, KICH, cholangiocarcinoma (CHOL), KIRP, PAAD, THYM, LGG, GBM, LUAD, LAML, and DLBC." (PMID 37698530, 2023).
colon cancer (1 paper, 2013). "A number of genes such as CCL20, CD36 and IL18RAP individually showed significant correlations with clinical variables in colon cancer such as tumor stage (T1 to T4), lymph node status (N0 to N2), metastasis (M0 or M1), pathological grade (G1 to G4) and Duke stage (A to D)." (PMID 23536776, 2013).
dengue (1 paper, 2025). "The associations between HERV expression, CXCR1, IL18RAP, and dengue severity represent insights that should be further investigated through functional assays and patient-derived immune cell models." (PMID 40124360, 2025). "Even with the challenges of directly interpreting in vitro transcriptomic findings in a physiological context, the concordance of our results with prior in vivo studies strengthens the suggestive potential role of CXCR1 and IL18RAP upregulation in severe dengue." (PMID 40124360, 2025). "Specifically, the upregulation of CXCR1 and IL18RAP genes in patients who progressed to severe dengue correlates with a complex regulatory network involving down-regulated microRNAs (miRNAs) and non-LTR retroviruses, emphasizing their relevance to inflammation and vascular permeability." (PMID 40124360, 2025). "Key findings demonstrate the up-regulation of immune-related genes, such as CXCR1 and IL18RAP, along with HERV elements and down-regulated miRNAs in severe dengue patients." (PMID 40124360, 2025).
E. coli infection (1 paper, 2019). "As for the eight common genes screened out in all four datasets, CEACAM1, GK, PFKFB3, and TNFAIP6 emerged repeatedly in the S. aureus group, but CEACAM1, IL18RAP, LILRA5, PFKFB3, PSTPIP2, and SOCS3 emerged in the E. coli infection." (PMID 31093495, 2019).
glioblastoma multiforme (1 paper, 2023). "Among them, kidney renal clear cell carcinoma (KIRC), kidney chromophobe (KICH), head and neck squamous cell carcinoma (HNSC), and glioblastoma multiforme (GBM) had higher levels of IL18RAP mRNA expression than normal tissues did." (PMID 37698530, 2023).
glomerulonephritis (1 paper, 2021). A renal disorder characterized by damage in the glomeruli. "Potentially, higher IL18RAP expression in the infiltrating neutrophils could enhance the generation of ROS, which is known to play a major role in glomerulonephritis." (PMID 33919154, 2021).
Hypertension (1 paper, 2021). The presence of chronic increased pressure in the systemic arterial system. "These same investigators also identified a correlation between expression of the IL-18 receptor accessory protein (IL-18RAP) and elevated blood pressure in a cohort of African American patients and suggested this protein as a possible novel immune target in hypertension." (PMID 33494430, 2021).
idiopathic dilated cardiomyopathy (1 paper, 2014). Decreased function of the heart associated with cardiac enlargement and congestive heart failure, of unknown cause. "It is interesting to note the importance of autoimmune related genes (IL18RAP and IL13R) in left ventricular hypertrophy or idiopathic dilated cardiomyopathy." (PMID 25329069, 2014).
left ventricular hypertrophy (1 paper, 2014). Enlargement of the LEFT VENTRICLE of the heart. "New discoveries include gene-based association of NSF with triglyceride levels and several genes (ACSM3, ERI2, IL18RAP, IL23RAP and NRG1) with left ventricular hypertrophy phenotypes." (PMID 25329069, 2014).
lumbar disc degeneration (1 paper, 2013). "Although our findings strengthen the evidence in support of previously reported association of IL18RAP gene variant with radiographic lumbar disc degeneration, we could not rule out that these findings could be by chance." (PMID 23522322, 2013).
metastasis (1 paper, 2020). The spread or migration of cancer cells from one part of the body (where they first appeared) to another. "Moreover, expression of individual genes in this panel, including IL18RAP, CXCL11, FCER1G, CSF3R and IL2RG were strongly linked to distant metastasis, lymph node metastasis, tumor stage, clinical stage or pathologic grade." (PMID 33049716, 2020).
nephritis (1 paper, 2021). Inflammation of renal tissue. "Results from our pilot screening assay on SLE peripheral leukocytes showed highly correlated expression between IL18RAP and neutrophil-associated genes, and the former was significantly elevated in patients with nephritis development." (PMID 33919154, 2021). "Taken together, our findings provide evidence to support an additional pathogenic role of IL-18 in that it may promote nephritis through the mediation of neutrophil dysfunction via the upregulated expression of IL18RAP." (PMID 33919154, 2021). "By qRT-PCR and Western blot analyses, elevated expressions of IL18RAP mRNA and protein were observed in neutrophils from SLE patients—particularly those with a history of nephritis." (PMID 33919154, 2021).
NKT cell lymphoma (1 paper, 2022). "This is a strong evidence of association between IL18RAP and NKT cell lymphoma (P < 1.0 × 10−6)." (PMID 35092558, 2022). "One study suggested that IL18RAP was helpful in tumorigenesis of NKT cell lymphoma." (PMID 35092558, 2022).
renal cell carcinoma (1 paper, 2021). "In renal cell carcinoma, the high expression of IL18RAP suggests a poor prognosis." (PMID 34631695, 2021).
systemic-onset juvenile idiopathic arthritis (1 paper, 2021). Systemic-onset juvenile idiopathic arthritis is marked by the severity of the extra-articular manifestations (fever, cutaneous eruptions) and by an equal sex ratio. "In systemic-onset juvenile idiopathic arthritis (SJIA), an overexpression of IL18RAP in neutrophils was observed in patients with active disease." (PMID 33919154, 2021).
testicular germ cell tumor (1 paper, 2023). A germ cell tumor arising from the testis. "According to the findings, IL18RAP mRNA levels were increased in the GBM, HNSC, KIRC, PAAD, and testicular germ cell tumors (TGCT)." (PMID 37698530, 2023).
Ventricular hypertrophy (1 paper, 2014). Enlargement of the cardiac ventricular muscle tissue with increase in the width of the wall of the ventricle and loss of elasticity. "Gene IL18RAP is weakly associated (p-value 5.07×10−21) with white cell counts (white cells, neutrophils, lymphocytes), with alanine transaminase (ALT) and glucose, but also with ECG measures of ventricular hypertrophy." (PMID 25329069, 2014).
tumor (14 papers, 2013 to 2024). "For most cancers, IL18RAP was positively linked to the immune and stromal score and negatively linked to tumor purity, indicating that IL18RAP may affect tumor progression by encouraging stromal and immune cell infiltration in the TME." (PMID 37698530, 2023). "Additionally, this study emphasized the connection between pancancer-level IL18RAP expression and clinical prognosis, DNA methylation, tumor mutation burden (TMB), TME, microsatellite instability (MSI), and immunotherapy." (PMID 37698530, 2023). "IL18RAP is associated with HCC prognosis and is important for immune cell infiltration into the tumor microenvironment." (PMID 37957902, 2024). "In this study, based on bioinformatics analysis, we discovered that IL18RAP is related to the human tumor microenvironment and promotes various immune cells infiltration." (PMID 37698530, 2023). "NK cells, CD8+ T cells, and M1 macrophages are key to the killing of tumor cells in vivo, and our analysis revealed that IL18RAP can promote CD8+ T cells and M1 macrophages infiltration in various cancers." (PMID 37698530, 2023). "Across several cancers, IL18 receptor accessory protein (IL18RAP) is abnormally expressed, and this abnormality is related to tumor immunity and heterogeneous clinical outcomes." (PMID 37698530, 2023). "In summary, IL18RAP can enhance the infiltration of multiple immune cells in a variety of cancers, thereby inhibiting tumor progression." (PMID 37698530, 2023). "We found that numerous NK cell effector function-related genes, such as TBX21, FYN, NCR1, SH2D1A, SH2D1B, PTPN6, and IL18RAP, were downregulated in tumor-infiltrating NK cells." (PMID 34535671, 2021). "In short, our study showed that IL18RAP is a new tumor biomarker and may become a potential immunotherapeutic target in cancer." (PMID 37698530, 2023). "This suggests that IL18RAP is indeed a key gene in the regulation of tumor immunity." (PMID 37698530, 2023). "This could bring together T cells secreting notable amounts of IFNγ, TGBβ, IL32, and IL18RAP with myeloid/monocyte-derived cells in the tumor microenvironment." (PMID 33076479, 2020). "Research has also demonstrated that IL-18RAP may promote tumor cell metastasis." (PMID 39461030, 2024). "This further confirms that the prognosis of HNSCC is related to the expression of local CD8+ T-cells in the tumor, and compared to HPV tumors, IL-18RAP and SIGIRR are highly expressed in HPV+ tumors." (PMID 39461030, 2024). "In addition, IL-18RAP may be involved in the immune escape process of tumor cells." (PMID 39461030, 2024). "The results showed that mRNA levels of ATG10, IL18RAP, PRKCD, SLC11A1, and SPP1 differed between tumor tissues and normal tissues in most of the 33 cancer types." (PMID 34631695, 2021). "Next, we analyzed the expression of CXCL5, CXCL8, IL18RAP, and TREM2 in paired tumor and adjacent normal tissues." (PMID 33955820, 2021). "Among them, IL-1α, IL1RAP, IL18RAP, and SIGIRR may affect the prognosis of patients by affecting local CD8+ T cell infiltration in the tumor." (PMID 39461030, 2024). "This article explores the targets that affect local CD8+ T-cell infiltration in tumors and subsequently affect patient prognosis (IL-1A, IL1RAP, IL18RAP, SIGIRR), which may also become a breakthrough in improving tumor treatment efficacy." (PMID 39461030, 2024). "IL18RAP, short for interleukin 18 receptor accessory protein, expresses the accessory β-subunit of the heteromeric receptor for IL18, a cytokine regulating the immunity by its pro-inflammatory effect and promoting tumor initiation and progression." (PMID 35092558, 2022).
cancer (12 papers, 2021 to 2025). A tumor composed of atypical neoplastic, often pleomorphic cells that invade other tissues. "Among which, IL18RAP was associated with activated CD4+ memory T cells in 24 cancer types, CD8+ T cells in 24 cancer types, and M1 macrophages in 27 cancer types in a positive correlation." (PMID 37698530, 2023). "Moreover, we also observed that IL18RAP expression was significantly negatively related to cancer-associated fibroblast and myeloid-derived suppressor cell infiltration levels in most cancers." (PMID 37698530, 2023). "In conclusion, our research offers comprehensive views of how IL18RAP affects clinical characteristics, gene alterations, gene modifications, immune infiltration, and immunotherapy in various human cancer." (PMID 37698530, 2023). "We discovered that IL18RAP was differentially expressed in various cancers, and the IL18RAP level was downregulated significantly in most cancers and correlated with clinical stage." (PMID 37698530, 2023). "Through gene correlation analysis, we validated the association between IL18RAP and known ICI genes in cancers." (PMID 37698530, 2023). "This provided more evidence that IL18RAP regulates the development of cancers by promoting the synthesis of INF-γ, which regulates T cell activation and improves NK cell killing." (PMID 37698530, 2023). "As a result of IL18RAP’s ability to modulate the immune system, its function in malignancies has also drawn attention." (PMID 37698530, 2023). "By using the GSCALite database, we explored the correlation between IL18RAP and well-known cancer-related pathways activated or inhibited across cancers." (PMID 37698530, 2023). "The findings supported the previous finding that IL18RAP expression was positively associated with CD8+ T cells and M1 macrophages in a number of cancers." (PMID 37698530, 2023). "Using the cBioPortal platform, we investigated the IL18RAP alteration sites, alteration frequency, and alteration type across cancers." (PMID 37698530, 2023). "Through further exploration, this study clarified the biological function of IL18RAP across cancers and its ability to predict the immunotherapy response." (PMID 37698530, 2023). "We learned from the TIMER2.0 database that there were significant differences between the levels of IL18RAP expression in various cancers and the corresponding normal tissues." (PMID 37698530, 2023). "In this research, we identified the IL18RAP mRNA expression level, clinical characteristics, and genetic alterations in cancers." (PMID 37698530, 2023). "Nevertheless, more research is still required to determine the precise impacts of DNA methylation on the IL18RAP levels in these cancers." (PMID 37698530, 2023). "Using the GTEx and TCGA databases, we investigated the IL18RAP expression in 33 different human cancers." (PMID 37698530, 2023). "We next investigated the relationship between DNA methylation and IL18RAP expression in human cancers utilizing the GSCALite platform since DNA methylation frequently impacts gene expression and cancer prognosis." (PMID 37698530, 2023). "The significance of IL18RAP in cancers has received little research despite being a significant factor of IL18 signaling." (PMID 37698530, 2023). "On this basis, we used the cytoHubba plugins to extract the top 10 related genes and calculated their correlation with IL18RAP in 33 types of cancers using Spearman correlation analysis." (PMID 37698530, 2023). "Following that, we investigated the relationship between the mRNA expression levels of IL18RAP and overall survival (OS) in 33 different types of human cancers using single variate Cox regression analysis." (PMID 37698530, 2023). "The TIMER2.0 database was then analyzed in order to further assess the relationship of IL18RAP expression and immune cells across cancers." (PMID 37698530, 2023).
cancer (continued). "Notably, IL18RAP is differentially expressed in various cancers, and its levels are significantly downregulated in most cancers and correlated with clinical staging." (PMID 39461030, 2024). "This suggested that the IL18RAP level could reflect the sensitivity of multiple cancer cell lines to anti-cancer drugs." (PMID 37698530, 2023). "This further highlights the inhibitory effect of IL18RAP on cancer progression." (PMID 37698530, 2023). "Thus, we again analyzed the mRNA expression levels of IL18RAP in pan-cancer based on GTEx and TCGA databases." (PMID 37698530, 2023). "In addition, other open database data show that the IL18RAP mutation frequency significantly affects OS and DSS in LUADLUSC and THCA patients, although the IL18RAP mutation frequency is low in human cancers." (PMID 37698530, 2023). "Our research shown that IL18RAP is positively related to both stromal and immune scores in cancers, suggesting that IL18RAP may enhance the infiltration of both stromal and immune cells in TME." (PMID 37698530, 2023). "Therefore, it is essential and meaningful to conduct a comprehensive pan-cancer analysis to reveal the IL18RAP’s potential biological functions in various cancers." (PMID 37698530, 2023). "This study revealed a negative correlation between DNA methylation and IL18RAP, which may account for the low levels of IL18RAP expression in many cancers." (PMID 37698530, 2023). "However, the expression of IL18RAP across cancers are still unclear, and its clinical significance and molecular biological role remain to be investigated." (PMID 37698530, 2023). "In addition, in human and mouse cancer cohorts, we found that the level of IL18RAP can predict the immunotherapy response." (PMID 37698530, 2023). "In order to determine whether IL18RAP expression in cancer cells is crucial for the infiltration of M1 macrophages, immunofluorescence staining and in vitro experiments were used for further investigation." (PMID 37698530, 2023). "The results of this study demonstrate that IL18RAP might be a new immunological and prognostic biomarker, offering a new target for cancer immunotherapy." (PMID 37698530, 2023). "In addition, the relationship between 22 different types of immune cells and IL18RAP expression across cancers was determined using the CIBERSORT algorithm." (PMID 37698530, 2023). "However, activation of the cell death program leads to the release of inflammatory mediators IL1A and IL18RAP, which continue to promote cancer development." (PMID 35923703, 2022). "At present, there are only a few reports on the application of IL18RAP in cancer." (PMID 33955820, 2021). "The exact role of IL18RAP, RGL4 and TMC7 in cancer and its potential as a therapeutic target or marker is still not well understood, and further research is needed to determine its full implications in the development and progression of cancer." (PMID 37171396, 2023). "Western blot demonstrated that ATG10, PRKCD, and SPP1 were highly expressed in cancer tissues, while IL18RAP and SLC11A1 expression in cancer tissues was lower." (PMID 34631695, 2021). "This is in line with our findings, which showed that the protective gene IL18RAP has a negative correlation with the infiltration of M2 macrophages, CAFs, and MDSCs in various cancers." (PMID 37698530, 2023). "Additionally, we explored the correlation between IL18RAP and five methyltransferases (DNMT3L, DNMT3B, DNMT3A, TRDMT1, and DNMT1) across cancers." (PMID 37698530, 2023). "Additionally, the relationship between the levels of IL18RAP expression and OS, progression free interval (PFI), and disease specific survival (DSS) in various cancers was investigated using Kaplan-Meier analysis." (PMID 37698530, 2023). "More investigations are required to determine the effect of DNA methylation and genetic changes on IL18RAP in cancers due to the lack of IL18RAP research in this area." (PMID 37698530, 2023).
cancer (continued). "IL18RAP also modulates the TME and impacts cancer progression through proinflammatory functions." (PMID 34136377, 2021). "Although we found that low levels of IL18RAP in MDA-MB-231 cells could enhance the proliferation, migration and invasion abilities, no research has yet explored the precise function of IL18RAP in these cancers." (PMID 37698530, 2023). "Additionally, low IL18RAP expression was related to worse DSS and PFI in a variety of cancers." (PMID 37698530, 2023). "Interestingly, we observed that IL18RAP is negatively related to M0 macrophages and M2 macrophages in various cancers, which may be the reason why the TIMER algorithm failed to count the correlation between IL18RAP and macrophages because the TIMER algorithm does not analyze macrophage subtypes." (PMID 37698530, 2023).
head and neck tumors (1 paper, 2024). "However, the expression of IL18RAP in head and neck tumors is still unclear, and its clinical significance and molecular biological role still need to be studied." (PMID 39461030, 2024). "In this study, it was found that IL-1α, IL-1β, IL1R1, IL1RL1, IL1F10, IL33, CASP1, and AIM2 were highly expressed in head and neck tumors, while IL1RN, IL1RAPL1, IL1RAPL2, IL18BP, IL18R1, and IL18RAP were low in expressed, which is consistent with previous literature." (PMID 39461030, 2024).